ACHE (acetylcholinesterase (Yt blood group))
Diseases named in the same sentence as ACHE in open-access papers (continued):
Sharing a sentence is not in itself a finding about the gene and the disease.
Cognitive impairment (continued). "Behavioral assessments (Novel Object Recognition, Morris Water Maze) quantified cognitive impairment in scopolamine-treated mice, complemented by histological (Nissl staining, BDNF IHC), biochemical (ACh, AChE, BChE), and molecular (BDNF, CREB) analyses of hippocampal and cortical tissues." (PMID 41007261, 2025). "AChE inhibitors that bind to either the PAS or both the CAS and PAS may simultaneously alleviate cognitive deficits and delay the neurodegenerative process by preventing the aggregation of Aβ peptides." (PMID 39684512, 2024). "One major debate within GWI research has been the effect of AChE inhibitors on these cognitive deficits as they should not cross the BBB and affect central cholinergic activity." (PMID 38919622, 2024). "The modification in AChE activity enhances ACh degradation, which reduces ACh receptor activation, resulting in negative effects on neurotransmission and increased cognitive impairment." (PMID 39661258, 2024). "However, there is still a lack of knowledge on the levels of the key cholinergic enzymes ChAT and AChE in CSF and plasma in untreated patients with AD and in individuals with mild cognitive impairment (MCI) or subjective cognitive impairment (SCI)." (PMID 34512307, 2021). "Souvenaid efficacy in terms of prevention of cognitive impairment seems to be superior to the treatment with AChE inhibitors or no treatment in this population." (PMID 33682712, 2021). "In contrast, no change in AChE-activity was observed in non-septic patients even with delirium or cognitive impairment." (PMID 33203376, 2020). "Thus, the expression of AchE and ChAT in the hippocampus and its relation to TMT-induced cognitive impairment in rats was examined." (PMID 32664537, 2020). "Interestingly, when assessing the acetylcolinesterase (AChE) activity by [11C]MP4A (11C-methyl-4-piper-idinylpropionate), an inverse correlation with the activity of AChE and cognitive impairment was observed in MS patients." (PMID 27695400, 2016). "Additionally, 5α-EAL (10 and 30 mg/kg per day, i.p.) significantly improves cognitive impairments of AD mice in behavioral tests including Barnes and Y-maze tests, and 5α-EAL could reduce the activity of AChE in the hippocampus and cortex of AD mice." (PMID 38954263, 2024). "Based on the scopolamine-induced cognitive impairment, we studied the behavioral phenotype of AD model mice and discovered that GPCRAC extracts at high doses markedly alleviate AD-related cholinergic dysfunction, as demonstrated by increased Ach content and ChAT activity and decreased AchE activity." (PMID 35295332, 2022). "To validate the gamma oscillation deficit as a feature of cognitive impairment, we investigated whether deficits in gamma oscillation in PSAPP mice could be rescued by the AChE inhibitor donepezil, which has been approved for the palliative treatment of cognitive impairment in AD patients." (PMID 35027883, 2021). "Taken together, in the present study we have demonstrated that FPE treatment could significantly normalize metabolic disorder and improve cognitive deficits in STZ-induced experimental diabetic mice, and this effect is likely related to inhibition oxidative stress and AChE activity in brain." (PMID 26060502, 2015). "The effects of POF on cholinergic system components, including AChE, have not been reported, but it is well known that ovarian hormones have an important role in learning and memory, and deprivation from these hormones has an important role in cognitive impairment and cholinergic dysfunction." (PMID 40827097, 2025). "On the other hand, AChE activity might lead to a lack of ACh and cognitive deficit." (PMID 37063992, 2023).
dementia (180 papers, 2006 to 2025). Loss of intellectual abilities interfering with an individual's social and occupational functions. "AChE had the strongest impact in predicting especially the later stages, with higher values linked to greater likelihood of AD Dementia." (PMID 41292640, 2025). "Since rivastigmine causes less inhibition of AChE in the striatum than in the cortex and hippocampus, it can also be administered to patients with dementia and Parkinson’s disease." (PMID 39717349, 2024). "While AChE declines in AD, with a loss of cholinergic neurons, BuChE activity progressively increases as the severity of dementia advances." (PMID 39717349, 2024). "The effect of AChE-Is on cognition is persistent over time and is associated with delayed institutionalization and reduced mortality in dementia." (PMID 37353809, 2023). "Increased activity of the brain AChE causes fast hydrolysis of acetylcholine in turn increases the risk for the progression of dementia." (PMID 37006627, 2023). "This study reveals that aspirin has the potential to inhibit the activity of AChE in circulation, a pathogenic molecular marker that has been known to be associated with dementia." (PMID 37509038, 2023). "The pharmacological agents currently used for the therapy of the AD-associated dementia comprise three acetylcholinesterase (AChE) inhibitors, donezepil, rivastigmine, and galantamine." (PMID 35600880, 2022). "The excessive activity of acetylcholinesterase enzyme (AChE) causes different neuronal problems, especially dementia and neuronal cell deaths." (PMID 33488178, 2020). "Previously it has also been reported that NAR has inhibitory effects on AChE activity and therefore it has the potential to be effective in dementia and associated disorders." (PMID 31945778, 2020). "The thought-provoking results suggested an onset of dementia in the 10 ppm MNPs exposed group, which is antagonistically associated with the decrease of ACh and increase of AChE." (PMID 31181856, 2019). "Although this strategy is likely to have increased awareness of dementia around the time of the October 2012 trend change for AChE inhibitors, we believe that the more likely cause of this change is the patent expiry of the drugs in this class." (PMID 29843807, 2018). "Anticoagulant therapy with DOACs may reduce cardiovascular risk factors in the development of the AD-related dementias, whereas inhibitors of AChE and/or BChE may restore the cholinergic transmission in the AD brain at different disease stages." (PMID 35807514, 2022). "Additionally, disruption in the proper targeting and inhibition of AChE expression by miR‐132 (due to the down‐regulation it this miRNA) have been further proposed to be causally linked with the progression of dementia after ischaemic stroke." (PMID 32293776, 2021). "The cholinergic hypothesis of AD postulates that degeneration of cholinergic neurons and the resultant decrease in the activity of AChE and depletion in the level of ACh are the immediate and consistent causes of the cognitive decline and dementia in neurodegenerative diseases." (PMID 33466604, 2021). "AChE inhibitors, which prevent the breakdown of ACh, are used to improve symptoms and slow the progression of AD and Parkinson’s disease dementia." (PMID 39857431, 2025). "Administration of Compound 4 (volvalerenic acid K) resulted in a significant, concentration-dependent decrease in AChE activity in the brain of the transgenic dementia mouse model (p < 0.01)." (PMID 40002547, 2025). "Scopolamine, acting as a muscarinic ACh receptor antagonist, significantly increases AChE activity in the cortex and hippocampus, contributing to its dementia-inducing effects." (PMID 38339117, 2024). "Previous reports have shown that abnormal central cholinergic system is closely related to the pathogenesis of dementia, and Evodia lepta acts on the cholinergic system by inhibiting AChE activity." (PMID 38284892, 2024).
dementia (continued). "The C. vulgare extract treatment of the rats with dementia preserved AChE activity in the hippocampus at the control level." (PMID 38339117, 2024). "The AChE and BuChE inhibitory properties of paeoniflorin prove its in vitro potential and benefit in the dementia of AD." (PMID 39735856, 2024). "Research has found that quercetin has acetylcholinesterase (AChE) inhibitory activity, antioxidant activity and anti- dementia-like activity." (PMID 39470545, 2024). "Clinical trials have demonstrated that the use of AChE inhibitors has a positive effect on daily functioning and reduces behavioral disturbances in individuals with senile dementia." (PMID 39796512, 2024). "In this research, resveratrol treatments (both pure and micellar) in dementia animals demonstrated AChE-inhibitory activity in the hippocampus and an ACh and monoaminergic preservation effect in both observed brain structures." (PMID 39684486, 2024). "The dysregulated AChE has a significant impact on availability of acetylcholine and AChE activity progressively diminishes as the severity of dementia advances." (PMID 38315232, 2024). "In a noteworthy study, anti-dementia effects of ellagic acid and its glucoside conjugate thru AChE inhibition in glutamate-treated SH-SY5Y human neuroblastoma cells have been experimentally reported." (PMID 37990185, 2023). "By inhibiting AChE activity, canagliflozin represents a compound that resembles AD-registered therapies in this respect, supporting the need for further evaluation in dementia clinical trials." (PMID 38004485, 2023). "There are reports suggesting that AChE impacts the progression of dementia diseases by increasing the expression of Aβ amyloid precursor, neuronal apoptosis and the aggregation of AChE-Aβ amyloid, which is more toxic than the protein itself." (PMID 36769043, 2023). "Phenolic compounds from flower extracts of Acacia dealbata showed significant biological activities, including antioxidant and inhibitory effects against acetylcholinesterase (AChE) in dementia." (PMID 36986610, 2023). "In our experimental model of dementia, multiple Sc administrations affected the cholinergic system by increasing AChE activity followed by a reduction in ACh levels and the inhibition of choline acetyltransferase (ChAT) activity." (PMID 35204256, 2022). "Lecithin has been tried out in the treatment of dementia, alone or in combination with an acetylcholinesterase (AChE) inhibitor." (PMID 36212684, 2022). "In order to determine if the beneficial memory effect of myrtenal was mediated by the modulation of the cholinergic system, its effect on ACh brain levels and AChE activity in the cortex and hippocampus of dementia rats were evaluated." (PMID 35204256, 2022). "In this respect, the inhibition of AChE has been recognized as a key factor in the treatment of AD, Parkinson’s disease, senile dementia, myasthenia gravis, and ataxia." (PMID 36226120, 2022). "This is in line with our previous studies where the furanocoumarins xanthotoxin and bergapten diminished the level of AChE and increased the antioxidative capacity in the hippocampus and prefrontal cortex in the scopolamine model of dementia in mice." (PMID 35039558, 2022). "Acetyl- (AChE) and butyrylcholinesterase (BChE) inhibitors are used, e.g., to treat dementias and myasthenia gravis." (PMID 35455397, 2022). "It is widely known that the anti-dementia effects of tacrine are in consequence of AChE inhibition in the brain." (PMID 36005148, 2022). "Recently, AChE biosensors were also successfully utilized for the determination of reversible inhibitors, e.g., anti-dementia drugs and aflatoxins." (PMID 36140061, 2022). "It is known that AChE inhibition is an efficient therapeutic for dementia through the rescue of cholinergic deficit." (PMID 35923682, 2022).
dementia (continued). "We also found that the cholinesterase inhibitor (AChE), at a dose used to treat dementia in AD, was potent in reducing the increased hypercapnic ventilatory response well below the level present in control APP_ mice." (PMID 35682682, 2022). "Conversely, the expression of acetylcholinesterase (AchE), an enzyme that degrades Ach, is activated in dementia patients." (PMID 33815562, 2021). "AChE activity was also observed to be lower in patients with early PD dementia, particularly in the cerebellar medial occipital cortex." (PMID 34502198, 2021). "Compared to 10 μM tacrine commonly used to treat degenerative brain diseases such as dementia by inhibiting AChE enzyme, ellagic acid glucoside showed 32% of AChE inhibition rate at a concentration of 50 μM." (PMID 34287737, 2021). "The acetylcholinesterase (AChE) inhibitors donepezil and rivastigmine are approved for use in AD and other dementias." (PMID 34638977, 2021). "Acetyl cholinesterase (AChE) inhibitors have been explored so far to relieve symptoms of dementia by activating the cholinergic system." (PMID 34885751, 2021). "Previous research in ethnopharmacology lead to identifying some potential AChE inhibitors from plant sources including those for memory disorders (Dementia) and neurodegenerative diseases such as AD1216–21." (PMID 32332809, 2020). "Extracts of Piper nigrum (fruit) and Curcuma longa (rhizome) also inhibited the AChE significantly which is considered one of the key targets for therapeutic strategies against dementia." (PMID 32806490, 2020). "Previous research suggests that neurodegenerative disease (dementia, Alzheimer’s, Parkinson’s etc.)can be treated through few possible pathways including – AChE inhibition, enhancement of cholinergic activity in CNS, anti-inflammatory and antioxidant activity." (PMID 32332809, 2020). "AChE inhibition is also considered as a remedial strategy for other types of neuronal disorders like dementia and Parkinson’s diseases." (PMID 32397979, 2020). "Inhibition of acetylcholinesterase (AChE) is currently the conformist strategy for the treatment of AD, senile dementia, ataxia, and Parkinson's disease." (PMID 33367123, 2020). "Since the termination of cholinergic transmission is influenced by the level of ACh, AChE-inhibiting drugs, such as tacrine, donepezil hydrochloride, and rivastigmine have been used to produce positive results in patients with dementia." (PMID 32679768, 2020). "Given this, the treatment of AD-related dementia is typically done through the use of acetylcholinesterase (AChE) inhibitors, such as donepezil." (PMID 33158153, 2020). "Two enzymes hydrolyzing the neurotransmitter acetylcholine — AChE and BChE, play important roles in the clinical course and pathogenesis of AD and AD-type dementia." (PMID 30890752, 2019). "AChE inhibitors, which increase levels of available ACh in synapses, are still prevalent medications against dementias." (PMID 31009936, 2019). "Low levels of ACh lead to cognitive impairment and dementia, thus the inactivation of AChE increases the pool of ACh and ameliorates the cognitive dysfunction associated with AD." (PMID 31430943, 2019). "For patients with mild‐to‐moderate dementia, AChE inhibitors enhance the effects of maintenance cognitive stimulation therapy and improve its cost‐effectiveness." (PMID 27739182, 2017). "In 2009, NICE revised its guidance on acetylcholinesterase (AChE) inhibitor treatment of patients with moderate dementia, recommending that treatment should stop at the severe stage." (PMID 27739182, 2017). "Inhibition of AChE is effective to improve cognitive performance in patients with AD 19, 33, implying that the AChE activity is increased in dementia." (PMID 26818681, 2016). "Many post-mortem studies investigating pathophysiological mechanisms of dementia have focused on alterations in functional components of the cholinergic system, such as AChE, the vesicular acetylcholine transporter (VAChT), nAChR, and mAChR." (PMID 26984612, 2016).
dementia (continued). "This has led to a variety of findings, such as cortical AChE being significantly reduced in Parkinson’s disease (PD), PD with dementia (PDD) and AD, as well as correlating with certain aspects of cognitive function such as attention and working memory." (PMID 26984612, 2016). "Pooled analyses demonstrated a significant inverse correlation between cortical AChE activity and Cornell Scale for Depression in Dementia scores (r=0.5, P=0.007)." (PMID 28725692, 2016). "Inhibition of AChE also serves as a strategy for the treatment of senile dementia, ataxia, myasthenia gravis, and Parkinson's disease." (PMID 26351513, 2015). "All γ-carboline-phenothiazine conjugates have been assessed as inhibitors of AChE and BChE, which are important for AD and/or AD-like dementia development and structurally close enzyme—CaE." (PMID 26281952, 2015). "These impairments were restored by treatment with AChE inhibitors that are used as anti-dementia drugs for AD35." (PMID 26246157, 2015). "The application of anti-AChE drugs is not limited to the treatment of AD, since anti-AChE drugs are applied to treat various forms of dementia including Parkinson’s Disease and dementia." (PMID 24918454, 2014). "All these pieces of evidences suggest that polyphenols are potent AChE and BChE inhibitors, thus warranting neuroprotection and improved cognitive functions in AD and related dementia." (PMID 23840922, 2013). "AChE inhibitors have therapeutic applications in AD, senile dementia, ataxia, myasthenia gravis and Parkinson’s disease." (PMID 23565355, 2013). "CSF 25OHD level was reduced in AD patients (P < 0.05), and CSF AChE activity was decreased both in patients with AD (P < 0.05) and other dementias (P < 0.01) compared to healthy controls." (PMID 24312390, 2013). "In our previously published work, we mentioned that B. vulgaris ethanolic extract has a competitive AChE inhibitory ability suggesting its use to alleviate over activity of AChE in dementia patients." (PMID 24007270, 2013). "Pathology of neurodegenerative diseases including AD includes deficiency of neuromediator acetylcholine, thus making acetylcholinesterase (AChE) inhibitors as important clinically relevant drugs in AD and other dementia." (PMID 23840922, 2013). "It has been shown that AChE inhibitors inhibit lipid peroxidation and increase glutathione level in the brain in the mice experimental model of dementia." (PMID 24159418, 2013). "In the present study, CSF 25OHD level was reduced in AD patients, and CSF AChE activity was decreased both in patients with AD and other dementias compared to healthy controls." (PMID 24312390, 2013). "Dual SERT and AChE inhibitors are being developed to treat both depression and dementia with a single agent." (PMID 23209830, 2012). "Enhanced levels of brain AChE activity and oxidative stress have also been noted in patients suffering form dementia of AD and other dementias." (PMID 18691432, 2008). "Notably, AChE expression was significantly higher in clinically-diagnosed dementia and MCI participants receiving cholinesterase inhibitors compared to untreated individuals (P=1.16×10−9; P<0.0001 after diagnosis adjustment)." (PMID 41292640, 2025). "In 1996, researchers discovered that dehydroevodiamine (DHED), a white crystalline powder of quinazoline alkaloid extracted from Evodiae Fructus (EF), may well inhibit acetylcholinesterase (AChE) in vitro and possessed anti-dementia effects in vivo." (PMID 39942659, 2025). "Gelsemium significantly reduced AChE activity in comparison to SCO-treated mice (p < 0.01).Gelsemium pre-treatment in SCO-injected mice profoundly decreased mRNA expression level of AChE in comparison to only SCO-treated dementia mice." (PMID 40002547, 2025). "Additionally, decreased levels of acetylcholine (ACh) and choline acetyltransferase (CAT), coupled with elevated acetylcholinesterase (AChE) in the brains of dementia patients, have been well established." (PMID 38339117, 2024).